TRPV1 (transient receptor potential cation channel subfamily V member 1)
Diseases named in the same sentence as TRPV1 in open-access papers (continued):
Sharing a sentence is not in itself a finding about the gene and the disease.
cancer (continued). "Recently, we suggested that the use of the membrane Transient Receptor Potential Vanilloid-1 (TRPV1) modulators regulated the HSR in cancer cells." (PMID 27200359, 2016). "Capsaicin (CPS), a natural active ingredient of green and red peppers, and a ligand of transient receptor potential vanilloid type 1 (TRPV1), has been showed potential in suppression of tumorigenesis of several cancers." (PMID 27729033, 2016). "Because TRPV1 is among major pH sensors expressed in cancer cells, we first examined the effects of an antagonist and agonist of TRPV1 and found the critical role of TRPV1 in acid-induced activation of the PI3K/Akt pathway in MM cells." (PMID 27626482, 2016). "A similar effect was also observed with TRPV1 overexpression in the human cancer cell lines, HeLa and Hek293." (PMID 25395667, 2014). "TRPV1 also has been shown to mediate both mechanical and thermal nociception in cancer models of rats and dogs." (PMID 24524628, 2014). "The specific roles of IB4(+) and TRPV1(+) neurons in the cancer microenvironment and their contribution to cancer pain need to be determined." (PMID 24524628, 2014). "We show in a mouse model that IB4(+) neurons play an important role in cancer-induced mechanical allodynia, while TRPV1 mediates cancer-induced thermal hyperalgesia." (PMID 24524628, 2014). "Capsaicin, the major TRPV1 agonist, has been shown to inhibit in vivo and in vitro cancer growth and progression and to induce apoptosis of different cancer cells." (PMID 24901005, 2014). "TRPV1 expression determined by Western blotting was weaker in the low grade carcinoma than in normal urothelium." (PMID 24868547, 2014). "The expression of TRPV1 decreased in low grade and even more in high grade carcinoma when compared with normal urothelium, while TRPV4 expression was unchanged in all samples." (PMID 24868547, 2014). "Former studies also showed that analgesia produced by EA with low frequency was accompanied by inhibition of TRPV1 up-regulation in sensory neurons in diabetic neuropathic pain, nerve growth factor-induced hyperalgisea, and cancer-induced pain." (PMID 23935654, 2013). "Cancer cells devoid of TRPV1 were unable to augment a HSR while introducing the TRPV1 into these cells restored this HSR capacity." (PMID 23468922, 2013). "Further basic studies on the structure, in vivo expression and function of the TRPV1 channel must to be conduced to completely understand the role of TRPV1 as tumor suppressor gene in cancers of epithelial origins." (PMID 22523714, 2012). "Then, as the tumor progresses, acceleration of acidification and chronic accumulation of formaldehyde lead to mechanical allodynia or severe pain via ASICs and/or TRPV1 in skin or bone marrow of the cancer patients." (PMID 20422007, 2010). "The expression of TRPV1 was elevated by 53% ± 0.07 in the ipsilateral DRGs (DRGs from cancer rats (TRPV1/Tubulin)/from sham rats (TRPV1/Tubulin) = 1.53 ± 0.07, p < 0.01)." (PMID 21118579, 2010). "TRPV1 currents were higher in cancer rats (453.3 ± 79.48 pA, n = 14) than that in sham-operated rats (253.6 ± 28.45 pA, n = 15, p < 0.05)." (PMID 21118579, 2010). "TRPV1 participates in nociception especially under acidic conditions and is considered to play an important role in cancer pain." (PMID 20422007, 2010). "Western blotting results showed that ipsilateral expression of TRPV1 in DRGs was higher in cancer rats (n = 6) than in sham rats (n = 6)." (PMID 21118579, 2010). "It is well known that transient receptor potential vanilloid receptor 1 (TRPV1) participates in cancer pain." (PMID 20422007, 2010). "In our behavior tests, we found that formaldehyde at low pathological (3 mM, based on concentration detected in human cancer tissues) in an acidic environment induced rat pain responses via TRPV1 in vivo." (PMID 20422007, 2010). "There were several studies on Transient receptor potential vanilloid 1 (TRPV1), the research on TRPV1 in cancer remains unclear." (PMID 41535811, 2026).
cancer (continued). "Importantly, TRPV1 expression correlated positively with cancer stem cell markers in both murine models and human samples." (PMID 41694593, 2026). "TRPV1 was significantly upregulated in 13 cancers, and was closely correlated with poor prognosis." (PMID 41535811, 2026). "Pharmacological modulators of specific TRPV1 channels may promote or induce cancer cell death, and may also be effective in reducing cancer cell proliferation, invasion, and metastasis." (PMID 40007993, 2025). "Notably, TRPV2 is implicated in inducing the death of various cancer cell types; however, many studies also indicate that the action of CBD is also mediated by the receptors TRPV1, TRPV4, CB1, CB2, and VDAC1." (PMID 40006844, 2025). "In addition, TRPV1 blockade reliably attenuated cancer pain-related hyperalgesia and PD-L1 analgesia, suggesting a crucial role of TRPV1 in PD-L1 signaling." (PMID 40002809, 2025). "Particularly, in cancer pain models, TRPV1 is expressed in larger DRG neurons than usual." (PMID 39940997, 2025). "Therefore, it is promising to regulate TRPV1 to restore the balance of the cell proliferation-apoptosis signaling pathway to achieve anti-cancer effects." (PMID 40007993, 2025). "However, in several painful conditions, ranging from diabetes to neuropathic pain and cancer pain, a change in TRPV1 localization and expression is possible in distinct subpopulations of DRG neurons." (PMID 39940997, 2025). "TRPV1 agonist combined with chemoradiotherapy is a feasible strategy for cancer treatment." (PMID 40007993, 2025). "In addition, We need to pay attention to the fact that TRPV1 regulators can inhibit cancer cell migration and invasion through non-TRPV1 pathways." (PMID 40007993, 2025). "TRPV1 mRNA and protein are expressed in many cancer cell lines, and the expression levels in different cancer tissues are significantly different from those in their normal tissues, suggesting that it is involved in key processes of cancer progression." (PMID 40007993, 2025). "The TRPV1 channels is a major driver of cancer-related pain." (PMID 40579593, 2025). "The data presented here thus suggest a possible role for endocannabinoids/endovanilloids in the pathogenesis of EC and although TRPV1 activation holds promise as a potential therapeutic target in certain cancers, it relevance and efficacy in EC warrant further investigation and validation." (PMID 40243844, 2025). "The researchers have demonstrated that NIR-mediated heating of GNRs can trigger the activation of TRPV1, inducing an increase in caspase activation, mitochondrial dysfunction, and DNA fragmentation, all of which culminate in the targeted destruction of cancer cells." (PMID 40813985, 2025). "However, their specific mechanisms and roles in different types of cancer are still not fully understood, and TRPV1 modulators still have a long way to go before becoming anti-tumor drugs due to their side effects." (PMID 40007993, 2025). "TRPV1 modulators can enhance the effect of chemoradiotherapy, and the synergistic use of TRPV1 modulator can reduce the required dose of chemoradiotherapy to control cancer and reduce the toxic side effects of chemoradiotherapy." (PMID 40007993, 2025). "Additionally, it explores the involvement of TRPML1, TRPA1, TRPM2, and TRPV1 in modulating reactive oxygen species (ROS) levels within cancer cells, analyzing the ROS dual role in tumor modulation." (PMID 40813985, 2025). "Additionally, transient receptor potential vanilloid (TRPV) channels, particularly TRPV1, have gained considerable attention in the context of cancer pain, especially CIPN." (PMID 40579593, 2025). "However, the expression level of TRPV1 in some cancer tissues was lower than that in their normal tissues." (PMID 40007993, 2025). "TRPV1 are the potential link between inflammation, cancer, and immunity." (PMID 39940997, 2025). "TRPV1 is a significant modulator of pathways crucial for both cancer proliferation and inhibition." (PMID 39407657, 2024).
cancer (continued). "Therefore, TRPV1 can enhance the efficacy of chemotherapeutic agents, providing a synergistic approach to cancer treatment." (PMID 39407657, 2024). "For instance, TRPV1’s role in neuroimmune interactions presents a potential therapeutic target, but the therapeutic strategies aimed at modulating TRPV1 must be carefully designed, taking into account the specific cancer type and the unique characteristics of the tumor microenvironment." (PMID 39407657, 2024). "Cancer pain is reduced in TRPV1-null mice compared to in wild-types." (PMID 38339399, 2024). "Overall, these findings highlight the important role of TRPV1 channels in cancer-related pain." (PMID 39811726, 2024). "There is increasing evidence that TRPV1 plays a major role in cancer pain." (PMID 38339399, 2024). "Consequently, there is increased interest in examining the impacts of TRPV1 agonists and antagonists on cancer development." (PMID 39273976, 2024). "Because TRPV1 is involved in multiple pathways, it shows promise as a target for cancer therapies." (PMID 39407657, 2024). "Increasing TRPV1 expression blocks mitosis and induces apoptosis in different cancer cell lines." (PMID 38791297, 2024). "While the elimination of TRPV1-expressing nociceptor neurons reduces tumor growth and enhances survival rates, it also highlights a potential therapeutic target for mitigating depressive behaviors in cancer patients." (PMID 39302290, 2024). "However, emerging evidence suggests that TRPV1 is also involved in various physiological and pathological processes, including cancer." (PMID 38791297, 2024). "Also, when capsaicin, a compound from chili peppers, interacts with TRPV1, it elicits a “hot” sensation and influences cancer processes through calcium influx." (PMID 39407657, 2024). "Similarly, studies have shown that when TRPV1 is activated by capsaicin, it increases the expression of androgen receptors in prostate cancer cells through these same pathways, which helps the cancer cells grow and survive." (PMID 39407657, 2024). "The modulation of TRPV1 activity, whether through dietary compounds like capsaicin or targeted therapies, presents a promising avenue for future cancer treatments." (PMID 39407657, 2024). "Exploring TRPV1’s function in cancer could result in the identification of novel biomarkers and therapeutic targets, thereby advancing cancer diagnosis and treatment." (PMID 39407657, 2024). "However, the impact of TRPV1 activation on cancer progression is unclear, with studies producing varying outcomes." (PMID 39407657, 2024). "Understanding TRPV1’s multifaceted roles in cancer may lead to novel therapeutic strategies for managing cancer-related symptoms and improving patient outcomes." (PMID 39407657, 2024). "Is there a role for per os TRPV1 antagonists in cancer pain relief?" (PMID 38339399, 2024). "Therefore, the observation that TRPV1 antagonists ameliorate cancer pain in rodents should be considered with reservations." (PMID 38339399, 2024). "Sensory afferents that express the capsaicin receptor TRPV1 play a central role in cancer pain." (PMID 38339399, 2024). "The expression profile of TRPV1 and innate immunity toll-like receptor 4 (TLR4) was also assessed in the L3–5 DRG sensory neurons, corroborating the association between these two receptors based on their co-expression on DRG cells of the cancer-induced model." (PMID 38730655, 2024). "Similarly, the modulation of immune cells by TRPV1 activation extends its influence beyond direct tumor cell survival, potentially altering the tumor microenvironment and affecting cancer progression through immune evasion mechanisms." (PMID 39407657, 2024). "Furthermore, the IL-23/IL-17A/TRPV1 axis is crucial for mechanical pain via macrophage–sensory-neuron crosstalk in female mice, which is relevant to cancer pain management and the tumor microenvironment." (PMID 39407657, 2024). "Emerging research underscores TRPV1’s therapeutic potential across various cancer types." (PMID 39407657, 2024).
cancer (continued). "Different TRPV1 agonists or antagonists had effects on cancer cell proliferation." (PMID 38612571, 2024). "Collectively, these studies illustrate the broad therapeutic potential of TRPV1 modulation, with capsaicin emerging as a promising component in enhancing cancer treatment efficacy and managing inflammatory conditions through targeted activation and signaling pathways." (PMID 39407657, 2024). "The complex interplay of TRPV1—where its activation can either promote cancer cell survival or enhance apoptosis—highlights the complexity and relevance of targeting this channel in cancer therapy." (PMID 39407657, 2024). "Normal cells have low to no expression of TRPV1 compared to cancer cells; therefore, they are less susceptible and sensitive to calcium changes induced by the activation of TRPV1 channels." (PMID 38791297, 2024). "Blockade of the SN TRPV1 action may be a potential therapeutic approach for cancer progression in bone and its complications such as bone pain and secondary metastasis to visceral organs." (PMID 37461623, 2023). "Lastly, the potential use of TRPV1 modulators in cancer therapy is discussed." (PMID 37371563, 2023). "Through interaction with a ligand called capsaicin, TRPV1 also regulates the release of pain-relieving chemicals in the brain, which suggests that it may also play a role in cancer pain." (PMID 37189782, 2023). "TRPV1, a ligand-activated membrane ion channel, functions in both apoptotic cell death and proliferation, constitutes a promising target in anti-cancer therapies." (PMID 37025492, 2023). "The agonists and the antagonists of TRPV1 raised the interest of many groups in cancer therapy." (PMID 37507867, 2023). "A recent pan-cancer study further cemented the prognostic value of tumoral TRPV1 expression." (PMID 37371563, 2023). "Moreover, TRPV1 expression was found to be markedly lower in late-stage (stage III-IV) cancers, and TRPV1 downregulation correlated with worse overall survival." (PMID 37371563, 2023). "Further studies are warranted to tailor specific TRPV1-based approaches for cancer therapy as some cancer patients may respond to TRPV1 agonists whereas others may benefit from TRPV1 blockade." (PMID 37371563, 2023). "If the TRPV1 on cancer cells is functional, RTX may suppress cancer pain and decrease tumor volume at the same time." (PMID 37894723, 2023). "IGF-1 may contribute to pain pathogenesis in cancer by upregulating the expression and function of TRPV1." (PMID 37242543, 2023). "Regarding TRPV1, two cancer clinical trials have been reported so far." (PMID 37892239, 2023). "Taken together, we conclude that TRPV1 inhibition could overcome the cisplatin resistance of tumor cells and represent an attractive strategy for the control of human cancer as a synergistic agent with cisplatin treatment." (PMID 37165076, 2023). "Little is known about TRPV1 and cancer-induced chemosensitivity." (PMID 37892239, 2023). "Among them, those genes related to binding might be responsible for cancer cell apoptosis and migration, revealing a potent ability of TRPV1 blockade to synergize thermotherapy." (PMID 37120615, 2023). "Furthermore, drugs targeting TRPV1, such as resiniferatoxin, have shown promise in alleviating severe adverse effects endured by cancer patients during chemotherapy and managing cancer-related pain." (PMID 38188686, 2023). "TRPV1 was identified as the neuronal receptor for harmful stimuli, which may allow the development of treatment of chronic pains including cancer." (PMID 37507999, 2023). "Consequently, TRPV1 represents a pharmacological target for pain treatment, including chronic pain, cancer pain, neuropathic pain, and musculoskeletal pain." (PMID 37765025, 2023). "Patients with TRPV1-positive carcinoma had a better prognosis." (PMID 37240443, 2023). "Nevertheless, some studies have revealed a tumor suppressor role of TRPV1 in various cancers." (PMID 36304985, 2022).